KLF9 (KLF transcription factor 9)
Diseases named in the same sentence as KLF9 in open-access papers (continued):
Sharing a sentence is not in itself a finding about the gene and the disease.
Hyperglycemia (7 papers, 2019 to 2025). An increased concentration of glucose in the blood. "A mutation in KLF9 eliminates the stimulatory effect of Dex on cellular glucose output and effectively attenuates Dex-induced hyperglycemia, a critical finding for patients requiring long-term glucocorticoid therapy." (PMID 38516000, 2024). "Very recently, it was shown that Klf9 induction by synthetic GCs in mouse liver leads to hyperglycemia, while deletion of Klf9 caused hypoglycemia and was protective in a model of GC-induced diabetes." (PMID 34992551, 2021). "Similarly, KLF9, a transcription factor, regulates gluconeogenesis and is linked to hyperglycemia under stress conditions, such as chronic inflammation in T2DM." (PMID 40282289, 2025). "Meanwhile, myeloid Klf9 deficiency also relieved Dex-induced hyperglycemia and hyperlipidemia." (PMID 38331933, 2024). "Our previous study indicates Dex-inducible KLF9 stimulates PGC1α, a master regulator of hepatic gluconeogenesis, thereby inducing hyperglycemia and glucose intolerance." (PMID 38331933, 2024). "Kruppel-like factor 9- (klf9-) mediated GR activation induces hepatic gluconeogenesis and hyperglycemia." (PMID 34745420, 2021). "Klf9 is a GR target that is ubiquitously expressed, including in the brain wherein it directs a maladaptive response to chronic stress, and in the liver where its overexpression contributes to hyperglycemia." (PMID 34692682, 2021). "KLF9 promotes the expression of peroxisome proliferator-activated receptor γ coactivator 1α (PGC1α), resulting in hepatic gluconeogenesis, and it is involved in glucocorticoid-induced hyperglycemia and diabetes." (PMID 31849586, 2019). "Induction of hepatic klf9 by dexamethasone promotes gluconeogenesis and hyperglycemia via PPAR activation, while klf9 knockout animals display hypoglycemia." (PMID 34692682, 2021).
osteosarcoma (6 papers, 2021 to 2025). A usually aggressive malignant bone-forming mesenchymal neoplasm, predominantly affecting adolescents and young adults. "As a result, the expression level of KLF9 was significantly diminished in the both osteosarcoma cells compared with that in hFOB1.19 cells." (PMID 35399713, 2022). "The result manifested that NRCAM expression level was obviously diminished with high KLF9 expression in the both osteosarcoma cells." (PMID 35399713, 2022). "The result showed that luciferase activity in the WT miR-338-3p promoter was increased in the two osteosarcoma cells with high KLF9 expression, which was significantly rescued by miR-338-3p inhibitor." (PMID 35399713, 2022). "After this, western blot analysis was adopted to assess the effect of KLF9 on NRCAM in the both osteosarcoma cells." (PMID 35399713, 2022). "Previous studies have found that Kuppel-like factor 9 (KLF9) is a potential target gene of miR-652 and participated in the regulation of proliferation and invasion of osteosarcoma by miR-652." (PMID 34608826, 2021). "Moreover, previous studies suggested that KLF9 played a vital role in the progression of various bone related diseases such as rheumatoid arthritis and osteosarcoma." (PMID 40016915, 2025). "Taken together, these outcomes indicated that KLF9 could directly regulate the expression and activity of miR-338-3p in osteosarcoma cells." (PMID 35399713, 2022). "We also found that KLF9 overexpression could raise the expression level of miR-338-3p in the two osteosarcoma cells." (PMID 35399713, 2022). "In addition, we also verified that high KLF9 expression could inhibit osteosarcoma cells' proliferation, invasion and migration." (PMID 35399713, 2022). "In addition, we found that overexpression of KLF9 could enhance the expression level of miR-338-3p in osteosarcoma cells." (PMID 35399713, 2022). "In addition, we confirmed that the KLF9/ miR-338-3p/NRCAM axis yielded a critical effect on proliferation, invasion and migration in osteosarcoma." (PMID 35399713, 2022).
pancreatic cancer (6 papers, 2019 to 2025). "To verify this hypothesis, we first examined the association of KLF9 with PAFAH1B3 in pancreatic cancer tissues and cells." (PMID 38649699, 2024). "In pancreatic cancer, KLF9 similarly demonstrates low expression, and this is associated with the degree of differentiation as well as the depth of vascular invasion." (PMID 40860800, 2025). "In pancreatic cancer, overexpression of KLF9 can inhibit Bcl-2 and induce cell apoptosis, demonstrating the important role of KLF9 in regulating cell life death balance." (PMID 40860800, 2025). "Western blotting revealed that KLF9 negatively regulates the expression of PAFAH1B3 in pancreatic cancer tissues and cells." (PMID 38649699, 2024). "We also found that KLF9 inhibits the proliferation and metastasis of pancreatic cancer cells by downregulating PAFAH1B3 expression." (PMID 38649699, 2024). "In conclusion, our study indicated that KLF9 can inhibit the proliferation, invasion, migration and metastasis of pancreatic cancer cells by inhibiting PAFAH1B3." (PMID 38649699, 2024). "In conclusion, these results suggest that KLF9 inhibits the proliferation and metastasis of pancreatic cancer cells by downregulating PAFAH1B3 expression." (PMID 38649699, 2024). "KLF9 inhibits the proliferation, invasion and migration of pancreatic cancer cells and is a beneficial prognostic factor in PDAC23." (PMID 38649699, 2024). "We found that KLF9 expression is negatively correlated with PAFAH1B3 expression in pancreatic cancer tissues and cells." (PMID 38649699, 2024). "In conclusion, these results suggest that PAFAH1B3 expression is inhibited by KLF9 in pancreatic cancer tissues and cells." (PMID 38649699, 2024). "Second, rescue experiments further demonstrated that KLF9 inhibits the proliferation, invasion and migration of pancreatic cancer cells by inhibiting the expression of PAFAH1B3." (PMID 38649699, 2024). "A rescue experiment was performed to confirm that PAFAH1B3 mediated KLF9 to inhibit the proliferation, invasion and metastasis of pancreatic cancer cells." (PMID 38649699, 2024). "Our previous studies showed that KLF9 inhibits the proliferation, invasion and migration of pancreatic cancer cells." (PMID 38649699, 2024). "Notably, KLF9 contributes to cancer development in other malignancies, such as pancreatic cancer, prostate cancer, thyroid cancer, and bladder cancer." (PMID 40860800, 2025). "Rescue experiments showed that overexpression of PAFAH1B3 could partially attenuate the suppression of pancreatic cancer cell proliferation, invasion and migration induced by KLF9 overexpression." (PMID 38649699, 2024). "The upregulation of KLF9, a tumor suppressor in pancreatic cancer, may inhibit the progression of this cancer." (PMID 37370046, 2023). "The expression of KLF9 was found to be relatively low in pancreatic cancer tissue samples and cell lines, and KLF9 overexpression reduces pancreatic cancer cell proliferation, induces apoptosis, disrupts the S-phase cell cycle, and inhibits cell migration and invasion." (PMID 35609330, 2022). "The expression of KLF9 was low in pancreatic cancer and cutaneous squamous cell carcinoma, and the up-regulation of KLF9 might inhibit the proliferation of pancreatic cancer and cutaneous squamous cell carcinoma." (PMID 35877357, 2022). "It has been reported that KLF9 exhibited low expression in pancreatic cancer, and upregulation of KLF9 may inhibit the progression of pancreatic cancer." (PMID 31024853, 2019). "However, whether PAFAH1B3 is involved in the mechanism by which KLF9 inhibits pancreatic cancer progression remains unclear." (PMID 38649699, 2024). "Finally, we examined the regulatory effect of KLF9 on PAFAH1B3 at the pancreatic cancer cell level." (PMID 38649699, 2024). "Therefore, we hypothesized that KLF9 inhibits PAFAH1B3 expression in pancreatic cancer." (PMID 38649699, 2024). "However, our previous studies did not explore the mechanism by which KLF9 inhibits pancreatic cancer progression." (PMID 38649699, 2024).
pancreatic cancer (continued). "There was a negative correlation between KLF9 and PAFAH1B3 expression in pancreatic cancer tissues and cells." (PMID 38649699, 2024).
rheumatoid arthritis (6 papers, 2022 to 2025). A chronic, systemic autoimmune disorder characterized by inflammation in the synovial membranes and articular surfaces. "Recent studies have shown that hsa-miR-218-5p regulates the proliferation, apoptosis, autophagy and oxidative stress of rheumatoid arthritis synovial fibroblasts by targeting Kruppel like factor 9 (KLF9) and activating JAK2/STAT3 signaling pathway." (PMID 37525657, 2023). "KLF9 could mitigate inflammatory responses and cartilage damage in rheumatoid arthritis via the transcriptional regulation of its downstream gene." (PMID 40584820, 2025). "As a target of miR-218-5p, KLF9 controlled the autophagy, apoptosis, and oxidative stress by regulating the JAK2/STAT3 signaling pathway in rheumatoid arthritis synovial fibroblasts." (PMID 36846202, 2023). "KLF9 silencing increased ROS and MDA levels in rheumatoid arthritis." (PMID 40584820, 2025).
cervical cancer (5 papers, 2021 to 2023). A primary or metastatic malignant neoplasm involving the cervix. "In the present study, we observed an association of the expressions of TPD52, KLF9, miR-223, and PKCε with tumor stage, metastasis, and treatment status of cervical cancer patients." (PMID 35047407, 2021). "A similar study has also reported that elevated level of miR-223 alleviates the expression levels of PKCε and KLF9, and can serve as potential biomarker for cervical cancer." (PMID 37833790, 2023). "Studies have shown that altered expression of KLF9 is involved in breast, prostate, and cervical cancer." (PMID 37833790, 2023). "Herein, according to the GEPIA database, KLF9 is down-regulated in cervical cancer and correlated with staging." (PMID 35609330, 2022). "The lower expression of KLF9 was found in advanced cervical cancer and negatively correlated with SCD1." (PMID 35609330, 2022). "The expression level of KLF9 was down-regulated in cervical cancer tissues in accordance with the GEPIA database." (PMID 35609330, 2022). "The experimental results in this paper indicate that KLF9/SCD1 expression can regulate the Akt/GSK3β signaling pathway in cervical cancer cells." (PMID 35609330, 2022). "Together, SCD1 was negatively regulated by KLF9 and it activated the Akt/GSK3β signaling pathway to promote the malignant progression of cervical cancer cells." (PMID 35609330, 2022). "Relationship between TPD52, KLF9, PKCε, and miR-223 expression and clinicopathological features of cervical cancer." (PMID 35047407, 2021). "There was a 23-fold increase in TPD52 expression, a 2-fold increase in miR-223 expression, a 0.14-fold decrease in KLF9 expression, and a 0.05-fold decrease of PKCε expression in cervical cancer." (PMID 35047407, 2021). "The expression of KLF9 was found to be downregulated in the blood of cervical cancer patients (0.14 ± 1.6) relative to healthy controls." (PMID 35047407, 2021). "Hence, our study also aimed to identify the combined expression patterns of TPD52, KLF9, miR-223, and PKCε, and their relationship with clinicopathological features, and to investigate the diagnostic and prognostic value of these genes in cervical cancer patients." (PMID 35047407, 2021). "In our study, we have measured the co-expressions of TPD52, KLF9, miR-223, and PKCε in cervical cancer." (PMID 35047407, 2021). "In the current study, the co-expressions of tumor protein D52 (TPD52), KLF9, microRNA 223 (miR-223), and protein kinase C epsilon (PKCε) were evaluated in cervical cancer patients and a possible relation with disease outcome was revealed." (PMID 35047407, 2021). "For verification of the relationship between these blood-based biomarkers (TPD52, KLF9, miR-223, and PKCε) and cervical cancer, ROC curves were generated." (PMID 35047407, 2021). "The relative expressions of TPD52, KLF9, miR-223, and PKCε in cervical cancer patients were measured with respect to their clinical features." (PMID 35047407, 2021). "The expressions of TPD52, KLF9, miR-223, and PKCε were studied in the blood of 100 cervical cancer patients and 100 healthy controls using real-time PCR." (PMID 35047407, 2021). "In the case of KLF9, we observed its significantly reduced expression in cervical cancer patients relative to healthy controls." (PMID 35047407, 2021). "The finding of the KLF9/SCD1/Akt/GSK3β regulatory axis expands the pathogenesis of cervical cancer." (PMID 35609330, 2022). "Overall, we found that the expressions of TPD52 and miR-223 were increased 23- and 2-fold in peripheral blood of cervical cancer patients, respectively, whereas expressions of KLF9 and PKCε were 0.14- and 0.05-fold reduced in cervical cancer patients relative to healthy individuals." (PMID 35047407, 2021). "Elevated expressions of TPD52 and miR-223 and reduced expressions of KLF9 and PKCε in peripheral blood of cervical cancer patients may serve as predictors of disease diagnosis and prognosis." (PMID 35047407, 2021).
cervical cancer (continued). "Moreover, upregulation of the expressions of TPD52 and miR-223 and downregulation of the expressions of KLF9 and PKCε were found in peripheral blood of cervical cancer patients." (PMID 35047407, 2021). "Together, the present study indicates that SCD1 is negatively regulated by KLF9 and it activates the Akt/GSK3β signaling pathway to influence the proliferation, migration, invasion, and EMT process of cervical cancer cells." (PMID 35609330, 2022). "Following transcription factor Kruppel like factor 9 (KLF9) was discovered to be negatively correlated with SCD1, the regulatory role of KLF9 in the effects of SCD1 on cervical cancer cells and the signaling pathway was evaluated." (PMID 35609330, 2022). "Cervical cancer patients exhibit lower blood levels of KLF9 mRNA compared to healthy non-cancerous controls, suggesting the possible utility of KLF9 as a non-invasive biomarker for this cancer type." (PMID 38067370, 2023).
diabetes (5 papers, 2019 to 2023). "KLF9 promotes PGC1α expression and activates the hepatic gluconeogenic program, which is an underlying pathogenesis of glucocorticoid therapy-induced diabetes." (PMID 37391422, 2023). "Lastly, the induction of the adiponectin gene by KLF9 is clearly of follow-up interest from the related contexts of tumor suppression and insulin sensitivity (anti-diabetes)." (PMID 35406507, 2022). "Recently, Cui and colleagues demonstrated that KLF9 promotes the expression of peroxisome proliferator-activated receptor γ coactivator 1α (PGC1 α) resulting in hepatic gluconeogenesis and suggested that KLF9 may be responsible for the glucocorticoid therapy-induced diabetes." (PMID 31545826, 2019).
lung carcinoma (5 papers, 2021 to 2025). "To further explore how Mxi1-regulated miR-300 was associated with the lung cancer pathogenesis, we analyzed the potential target genes of miR-300, and identified KLF9, which has been reported to be a tumor suppressor." (PMID 35501353, 2022). "KLF9’s involvement in lung cancer, particularly non-small cell lung cancer (NSCLC), has been extensively studied, revealing its role as a tumor suppressor." (PMID 40860800, 2025). "Other KLF9-targeting miRNAs with oncogenic properties so far identified in human lung cancer cells include mi-R-660-5p, miR-20a-5p, and miR-300." (PMID 38067370, 2023). "The miR matrix for KLF9 in lung cancers is particularly striking and large, and thus is a potential drug target in this malignancy, providing KLF9 is indeed confirmed to be beneficial to lung cancer patient prognosis." (PMID 38067370, 2023). "To further investigate the effect of the KLF9/GADD34 axis on the tumor growth of lung cancer, we silenced GADD34 in A549 cells (human origin) and HCC827 cells (human origin) and evaluated the depletion of GADD34 by RT-qPCR." (PMID 35501353, 2022). "miR-300 suppressed the expression of KLF9, and KLF9 negatively regulated GADD34 expression in lung cancer cells." (PMID 35501353, 2022). "Collectively, these findings suggest that Mxi1 can inhibit lung cancer progression by regulating the miR-300/KLF9 axis and GADD34-mediated immunosuppression." (PMID 35501353, 2022). "An increasing body of evidence has demonstrated that downregulation of KLF9 facilitates lung cancer progression via enhancing lung cancer cell malignant properties." (PMID 35501353, 2022). "We furthermore revealed that miR-300 targeted KLF9 and decreased the protein expression of KLF9 in lung cancer cells." (PMID 35501353, 2022). "We also found that KLF9 expression was repressed in lung cancer, and that its repression induced malignant properties in lung cancer cells." (PMID 35501353, 2022). "Mxi1 or KLF9 elevation or miR-300 repression inhibited lung cancer cell proliferation, as evidenced by reduced Ki67 and PCNA expression, and lowered invasion and migration." (PMID 35501353, 2022). "Mechanistically, we have revealed that Mxi1 exerts an inhibitory effect on lung cancer progression via the miR-300/KLF9/GADD34 axis." (PMID 35501353, 2022). "Besides, elevated KLF9 expression can reduce lung cancer cell proliferation, migration, and invasion by negatively regulating GADD34." (PMID 40860800, 2025). "Similarly, overexpression of miR-141, which also targets the 3′-UTR of KLF9 mRNA, enhanced the proliferation and invasion in vitro of a human lung cancer cell line, effects which were partially reversed by forced expression of KLF9." (PMID 38067370, 2023). "Altogether, these results suggested that miR-300 could stimulate malignant properties of lung cancer cells by reducing KLF9." (PMID 35501353, 2022). "Cumulatively, Mxi1 could arrest malignant features of lung cancer cells by regulating the miR-300/KLF9 axis." (PMID 35501353, 2022). "This is consistent with a recent study demonstrating that KLF9 is downregulated in lung cancer." (PMID 35501353, 2022). "To test this speculation, we investigated whether KLF9 targeted GADD34 using an internet-based analysis tool (hTFtarget), which revealed that GADD34 could indeed be targeted by KLF9 in lung cancer." (PMID 35501353, 2022). "Therefore, we first analyzed the expression of KLF9 in surgical specimens from lung cancer patients via the GEPIA website using the dataset obtained from TCGA, which demonstrated that KLF9 was significantly downregulated in lung tumors." (PMID 35501353, 2022). "We proposed a hypothesis that Mxi1 played a suppressive role in MDSC-mediated immunosuppression in lung cancer progression by modulation of miR-300, which consequently regulates the activity of Kruppel-like factor 9 (KLF9)/growth arrest and DNA damage-inducible protein (GADD34) axis." (PMID 35501353, 2022).
lung carcinoma (continued). "Therefore, it is possible that KLF9 may suppress tumor progression in a GADD34 dependent manner in lung cancer." (PMID 35501353, 2022). "Taken together, these lines of evidence indicated that knockdown of KLF9 led to an increase in the expression of GADD34, and promoted the accumulation and immunosuppression of MDSCs, thereby promoting the lung cancer growth." (PMID 35501353, 2022). "Wnt3a/β-catenin, circSATB2, HIF-1α/COX-2, KLF9, and LMO7 in tumor-derived exosomes regulate genes or signaling pathways to promote proliferation and migration of lung cancer cells." (PMID 34511114, 2021). "However, the involvement of KLF9 in miR-300-regulated lung cancer progression has not hitherto been investigated." (PMID 35501353, 2022).